PAX3 (paired box 3)
Diseases named in the same sentence as PAX3 in open-access papers (continued):
Sharing a sentence is not in itself a finding about the gene and the disease.
benign tumors (1 paper, 2019). "Finally, FOXO1 data from 165 EOC tissues, 46 borderline tumors, 42 benign tumors, and 57 nonadjacent normal epithelial tissues, as well as PAX3 data from 167 EOC tissues, 42 borderline tumors, 31 benign tumors, and 70 nonadjacent normal epithelial tissues could be interpreted." (PMID 31823759, 2019). "To evaluate the protein expressions of FOXO1 and PAX3 in EOC, we analyzed FOXO1 and PAX3 protein levels in 212 EOC tissues, 57 borderline tumors, 153 benign tumors, and 79 nonadjacent normal epithelial tissues by IHC." (PMID 31823759, 2019).
PAX3 also shares sentences with these, for which no sentence is quoted: leukemia (4 papers); Hirschsprung disease (3); Waardenburg syndrome type 3 (3); albinism (2); aniridia (2); Branchio-oculo-facial syndrome (2); CHARGE syndrome (2); colon cancer (2); degenerative diseases (2); epilepsy (2); epithelial ovarian cancer (2); Hearing impairment (2); hemorrhage (2); liposarcoma (2); myelomeningocele (2); neurodevelopmental disorder (2); telecanthus (2); acute lymphoblastic leukemia (1); adolescent idiopathic scoliosis (1); Aganglionic megacolon (1); Aland island eye disease (1); alveolar soft part sarcoma (1); angiosarcoma (1); Arnold–Chiari malformation (1); B-cell CLL (1); bladder cancer (1); brainstem glioma (1); cervical cancer (1); chromophobe renal cell carcinoma (1); chronic myelogenous leukemia (1).
A further 58 diseases each share a sentence with PAX3 in 1 paper.